PIK3CA (phosphatidylinositol-4,5-bisphosphate 3-kinase catalytic subunit alpha)
Diseases named in the same sentence as PIK3CA in open-access papers (continued):
Sharing a sentence is not in itself a finding about the gene and the disease.
cancer (continued). "In cancer cells, PIK3CA activating mutations or deletions are common, and Akt overexpression prevents apoptosis or sustained activation of mTOR, and drug resistance occurs." (PMID 41050074, 2025). "Since then, extensive research has been directed toward understanding the frequency of PIK3CA mutations across different cancer types and their clinical implications on prognosis and response to therapy." (PMID 40508087, 2025). "In the current study, we investigated the presence of antigen-experienced T cells in TIL and memory PBL from patients with cancer, against shared PIK3CA mutations." (PMID 41410746, 2025). "The presence of HPV in HNSCC, by modulating A3A activity, promotes the accumulation of mutations in cancer driver genes, such as the PIK3CA gene, conferring a proliferative advantage to these cells." (PMID 40143363, 2025). "This aligns with broader findings in other cancers, where PIK3CA mutations are commonly associated with pathways promoting cell survival and proliferation." (PMID 40361470, 2025). "Gain-of-function mutations on the PIK3CA gene, which encodes PI3Kα, are found in a broad range of cancers." (PMID 40427108, 2025). "PIK3CA is one of the most frequently mutated oncogenes in cancer and therefore provides a strong candidate for drug development and targeting." (PMID 40427140, 2025). "The authors discovered that 10 of the 23 (43%) carcinoma samples exhibited somatic PIK3CA mutations." (PMID 40364006, 2025). "The most frequently mutated gene in CHEK2-deficient cancers was PIK3CA (n = 4 cancers, three cancer types)." (PMID 38848470, 2024). "They observed that immortalized cancer epithelial cells that have hotspot PIK3CA mutation (H1047R or E545K) were sensitive to the MTOR inhibitor, rapamycin, and its analog everolimus." (PMID 39056802, 2024). "We tested AutoEpiCollect’s pan-cancer vaccine design on common cancers containing prevalent PIK3CA mutations." (PMID 38671743, 2024). "PIK3CA mutations in human cancers occur in two hotspots: one in the helical domain (e.g., E545K) and the other in the kinase domain (H1047R)." (PMID 38194275, 2024). "Activation of the PI3K/AKT/mTOR pathway, driven by PIK3CA mutations, can confer a survival advantage to cancer cells, promoting uncontrolled proliferation and resistance to apoptosis." (PMID 39369580, 2024). "A prominent example is the PIK3CA gene that encodes p110α, which is commonly mutated or amplified in a variety of cancers." (PMID 38539472, 2024). "In human cancers, PIK3CA is frequently mutated, while the other two subunits are generally amplified and overexpressed." (PMID 38545256, 2024). "Since PIK3CA mutations are present in multiple types of cancer, the reliable detection of these hotspot mutations is a highly important tool to guide treatment, especially since alpelicib is widely used in the treatment of ER+/HER2- metastatic breast cancer." (PMID 39711963, 2024). "AutoEpiCollect inputs the filtered and optimized lists of predicted immunogenic epitopes into the population coverage analysis tool to calculate the filtered and optimized population coverages of a pan-cancer vaccine containing mutated PIK3CA epitopes." (PMID 38671743, 2024). "PIK3CA mutations are commonly found in these cancers and can predict responsiveness to PI3K inhibitors." (PMID 38304083, 2024). "Our findings highlighted several crucial aspects of PIK3CA mutations, factors affecting mutational distributions in multiple cancers, and their potential implications in cancer biology." (PMID 39054873, 2024). "In this study, we applied AutoEpiCollect’s vaccine design process to develop a pan-cancer epitope-based vaccine targeting PIK3CA-mutated cancers." (PMID 38671743, 2024). "Previous cancer vaccines targeting the PIK3CA gene primarily target small sets of missense mutations, thus reducing the scope and efficiency of the vaccine." (PMID 38671743, 2024).
cancer (continued). "The most common putatively actionable alterations across all of the 35 cancer types were mutations in PIK3CA, KRAS and PTEN." (PMID 38890488, 2024). "Nevertheless, a subset of cases exhibited a combination of clonal and subclonal mutations, highlighting the intricacy of PIK3CA mutation patterns within individual tumors and cancer types." (PMID 39054873, 2024). "PIK3CA mutations have also been shown to be oncogenic by promoting the growth of cancer cells as well as invasion." (PMID 39593139, 2024). "This analysis revealed that while PTEN mutations occurred in both single and multiple PIK3CA mutation cohorts, their distribution varied across different cancer types." (PMID 39054873, 2024). "For instance, activating mutations in the PIK3CA gene have been identified in a wide range of cancers, including breast, endometrial, cervical, colorectal, esophageal, gallbladder, non-small cell lung, ovarian, and gastric cancers." (PMID 39596452, 2024). "Double or multiple PIK3CA mutations occur in 10%–15% of PIK3CA‐mutant cancers, typically on the same allele." (PMID 39054873, 2024). "Aberrations in the PIK3CA gene, often in the form of activating mutations, have emerged as recurrent events in various cancer types, including TNBC." (PMID 39369580, 2024). "One of the most common alterations in human cancers is the PIK3CA mutation, which causes persistent activation of p110, enhanced lipid kinase activity, and subsequent activation of Akt." (PMID 38807154, 2024). "Many human CCM tissue samples harbored the same oncogenic PIK3CA GOF mutations that also occur in cancer and in other vascular anomalies." (PMID 38747293, 2024). "Alpelisib, an oral selective inhibitor of class I PI3K p110α, has demonstrated antitumor properties in preclinical studies, particularly in the PIK3CA-mutated cancer models." (PMID 39070139, 2024). "Subprotocol Z1F of the NCI-MATCH trial (phase II, NCT05490771) evaluated copanlisib, in patients with PIK3CA-mutated cancers, enrolling 35 patients, with 25 included in the primary efficacy analysis." (PMID 38730642, 2024). "In Matrigel-coated Boyden chamber assays, enhanced migration and invasion of cancer cells transformed with PIK3CA mutations were shown to depend on AKT1-mediated phosphorylation of cortactin." (PMID 38786098, 2024). "Endometriotic lesions also harbour cancer driver mutations such as PIK3CA, PTEN, ARID1A, KRAS, PPP2R1A, and β-catenin (CTNNB1)." (PMID 38893278, 2024). "According to the TCGA, the characteristic gene aberrations for HPV-associated cancers include PIK3CA, DDX3X, CYLD and FGFR mutations." (PMID 39120301, 2024). "Detection of PIK3CA mutations in primary tumors and liquid biopsy samples is of increasing importance for treatment decisions and therapy resistance in many types of cancer." (PMID 39711963, 2024). "The highest values of PIK3CA expression were observed in the mesenchymal subtype (CMS 4) which is associated with aggressive cancer development and poor prognosis." (PMID 38891994, 2024). "PIK3CA mutations contribute to cancer development by affecting cellular growth and proliferation processes." (PMID 39685930, 2024). "This study aimed to further our understanding of the role of multi‐PIK3CA mutations in various cancers and will hopefully contribute to the optimization of targeted therapies." (PMID 39054873, 2024). "Alpelisib, an orally bioavailable PI3K inhibitor that selectively targets the p110α isoform, has demonstrated sensitivity in PIK3CA-mutated cancers in preclinical models and in Phase I trials involving patients with advanced solid tumours." (PMID 39769028, 2024). "PIK3CA mutation as one of the major driver oncogenes in cancer, the significance of PIK3CA mutations in cancer has been elucidated in many studies." (PMID 38704377, 2024).
cancer (continued). "Cancer cases that harbored the activating mutation PIK3CA H1047R in the coding exon 20 (a kinase-activating mutation) reliably respond to Alpelisib treatment." (PMID 39394200, 2024). "The targeting of these hotspot regions by a large number of our final epitopes enhances our vaccine’s utility and emphasizes its potential efficacy in addressing the major molecular drivers of PIK3CA-mutated cancers." (PMID 38671743, 2024). "Approximately 80% of PIK3CA mutations in human cancers are observed in hot spot regions, that is, exon 9 (E542K and E545K) and exon 20 (H1047R)." (PMID 38616230, 2024). "Mutations in the gene encoding the catalytic α-subunit of PI3K (PIK3CA) drive cancer proliferation and metastasis pathways and are found in approximately 30-40% of HR+/HER2– tumors." (PMID 38310616, 2024). "Their analysis indicated that the influence of PIK3CA mutations likely hinges on cancer subtypes and mutation sites." (PMID 39329702, 2024). "This study highlights the immunogenic potential of a cancer vaccine consisting of virtually predicted epitopes targeting missense mutations in PIK3CA." (PMID 38671743, 2024). "In our pan‐cancer cohort of 49 patients with multiple PIK3CA mutations, 88% (43 patients) exhibited double‐PIK3CA mutations." (PMID 39054873, 2024). "In this study, we analyzed multi‐PIK3CA mutations across a diverse pan‐cancer cohort comprising 3564 tumors." (PMID 39054873, 2024). "In this study, we conducted a comprehensive analysis of PIK3CA mutations across various cancer types, with a focus on cases exhibiting multiple PIK3CA mutations." (PMID 39054873, 2024). "Several cancers, including those of the breast, ovarian, lung, brain, and stomach, have been linked to PIK3CA mutations in this gene." (PMID 38807154, 2024). "Another study found that aspirin at physiologically attainable levels has a strong anti-cancer effect in those with a PIK3CA mutation compared to the wild type." (PMID 39445288, 2024). "Mutations in PIK3CA, the oncogene coding for p110α seems to be the most commonly mutated gene in various cancer types like liver, colorectal and breast." (PMID 38774756, 2024). "Most PIK3CA mutations associated with LM and cancer cluster at three specific “hot spots” located in the helical domain (E542, E545) and the kinase domain (H1047) of PI3Kα." (PMID 38488007, 2024). "The PIK3CA oncogene is one of the most frequently mutated oncogenes in all human cancers, and it is a typical target for cancer therapy." (PMID 38610953, 2024). "We used AutoEpiCollect to design a pan-cancer vaccine targeting missense mutations found in the proto-oncogene PIK3CA, which encodes the p110ɑ catalytic subunit of the PI3K kinase protein." (PMID 38671743, 2024). "We previously found KMT2D mutations associated with PIK3CA H1047R mutation in an invasive mammary carcinoma, where these two genes were the only cancer-driving genes mutated in this particular tumor." (PMID 38786098, 2024). "In cancer, PIK3CA is most frequently mutated, with mutations in AKT1, AKT2, and the proteins of the mTOR complex, except for RICTOR and mTOR, being relatively uncommon." (PMID 38473265, 2024). "Although our study presents some interesting findings, it was limited by the relatively small sample size of cases with multiple PIK3CA mutations in some cancer types." (PMID 39054873, 2024). "The significance in mutational status of APC and PIK3CA between the two different cancer types is dominated by male patients with sCRC." (PMID 39390564, 2024). "For instance, in nearly 15% of HPV-associated head and neck squamous cell carcinoma cases, A3-mediated mutations in key oncogenes like PIK3CA are observed, highlighting the role of A3 enzymes in driving genetic alterations that lead to cancer." (PMID 39764440, 2024).
cancer (continued). "We found that composite mutations occur in 5% of cancer patients, mostly affecting the PIK3CA, EGFR, BRAF, and KRAS genes, which are common precision medicine targets." (PMID 38757376, 2024). "Mutations in PIK3CA are often found in cancers located in the proximal colon and are associated with a high level of CpG island methylator phenotype (CIMP)." (PMID 38737656, 2024). "PIK3CA mutations are implicated in various cancers, but the implications of multiple concurrent mutations and their orientations within the gene have not been fully explored." (PMID 39054873, 2024). "After analyzing 49 PIK3CA point mutations across five different cancer subtypes, we received 361 potentially immunogenic MHC Class I epitope/HLA pairs and 219 MHC Class II epitope/HLA pairs." (PMID 38671743, 2024). "PIK3CA mutations were identified in 13.0% (474/3564) of samples in the pan‐cancer cohort, with the highest prevalence observed in uterine/endometrial (42.3%), breast (35.1%), cervical (27.7%) and ovarian (21.6%) cancers." (PMID 39054873, 2024). "The prevalence of PIK3CA mutations in the DE group (36.4%) was almost as high as in all other H2L carcinomas groups (1+ and 2+ NA carcinomas) together (p = 0.0227)." (PMID 38893129, 2024). "This is consistent with luminal molecular profiles since PIK3CA mutations have been reported to be present in approximately 25–45% of luminal A and B carcinomas, with a much lower prevalence (9%) in basal-like carcinomas." (PMID 38893129, 2024). "The global activation analysis of the three pathways (ssGSEA) according to the presence of a PIK3CA-activating mutation showed a strong activation of signaling pathways in carcinomas carrying such a mutation." (PMID 38893129, 2024). "PIK3CA mutations were more prevalent in H2L carcinomas, leading to a strong activation of the PI3K-AKT signaling pathway even in the absence of HER2 overexpression/amplification." (PMID 38893129, 2024). "Mutations in PIK3CA play important roles in the onset and development of cancer and are found to have a rate of 2–7% in NSCLC, especially squamous cell lung carcinoma." (PMID 36959802, 2023). "Our analysis also revealed species-specific mutational hotspots, including PIK3CA E545/2K mutations found only in human cancers." (PMID 37414794, 2023). "MEN1611, similar to alpelisib, targets with the highest potency the p110α wild-type and mutated isoforms, but is more effective than alpelisib in inhibiting the growth of cancer cell lines with PIK3CA-wt and PTEN-loss genetic background." (PMID 36913051, 2023). "In a study which performed whole exome sequencing of matched normal tissue and cancer from a range of tissues of 392 patients, PIK3CA mutations were most commonly found in both cancer and normal tissue." (PMID 37573406, 2023). "Compared to normal esophageal tissue, PIK3CA was significantly overexpressed in ESCC cancer tissue and its overexpression wasn indepenedently associated with higher risk of local recurremce." (PMID 36661697, 2023). "PIK3CA is the most commonly mutated of the PI3K subunit genes across all human cancers, and while infrequent in UC (5–10% of all UC cases and 20% of high-grade invasive cases), mutations of PIK3CA are associated with a poor prognosis." (PMID 37079639, 2023). "As in endometriotic tissue, PIK3CA was observed to be the most frequently mutated cancer driver gene in normal endometrial tissue." (PMID 37573406, 2023). "This cancer presents a low frequency of PIK3CA mutations (5%) but a high percentage of KRAS oncogenic alterations (90%), responsible for the global activation of the PI3K/AKT pathway." (PMID 36765741, 2023).
cancer (continued). "Another important pathway is associated with activating mutations in the phosphatidylinositol-4,5-bisphosphate 3-kinase catalytic subunit alpha (PIK3CA) gene occurring in approximately 30–40% of patients with cancer." (PMID 37427115, 2023). "Activating hotspot mutations in both the KRAS and PIK3CA oncogenes were present in both benign and malignant tumors." (PMID 36635367, 2023). "Activating mutations in p110α are frequent in malignant tumours, with the gene encoding p110α, PIK3CA, being the second most frequent oncogene in human cancer." (PMID 37050317, 2023). "PIK3CA is the most frequently mutated oncogene in human cancer and occurs in more than 30% of colorectal cancers." (PMID 37512582, 2023). "Oncogenic mutations are frequent in the class IA PI3K encoded by PIK3CA, with this being the second most frequently mutated gene in human cancer." (PMID 37417733, 2023). "We will perform a comparative meta-analysis for GOF PIK3CA point mutations in an attempt to demonstrate the genetic similarities shared by both cancers and vascular anomalies." (PMID 37109059, 2023). "PIK3CA gene mutations occur with higher frequency in colorectal (17.7%), small bowel (16.1%), and gastric (12.5%) cancers and with lower frequency in appendiceal cancers (~6.5%)." (PMID 37509254, 2023). "With a half-maximum inhibitory concentration in vitro on p110α less than 5 nM, compared to more than 1150 on p110β, alpelisib has demonstrated major antitumor activity in various preclinical models of cancer, notably when associated with PIK3CA alterations." (PMID 36900211, 2023). "PIK3CA encoding the phosphoinositide 3-kinase (PI3K) p110α catalytic subunit is frequently mutated in cancer, with mutations occurring widely throughout the primary sequence." (PMID 36635288, 2023). "A majority of CCM lesions are driven by a cancer-like three-hit mutational mechanism, including a somatic, activating mutation in the oncogene PIK3CA, as well as biallelic loss-of-function mutations in a CCM gene." (PMID 37919320, 2023). "This inhibitory interaction in class IA PI3Ks is disrupted in human cancers (helical hotspot mutations in PIK3CA) and immune disorders (helical mutations in PIK3CD in APDS1)." (PMID 37417733, 2023). "Since most PIK3CA mutations in cancers show gain of function and growth advantages, it was concluded that the presence of the same mutations in endometriotic epithelial cells has functional significance in the pathogenesis of the disease." (PMID 37005590, 2023). "It was recently found that the proliferation and survival of cancer cells carrying a PIK3CA mutation, as is HT29, is sensitive to the TCA cycle enzyme 2-oxoglutarate dehydrogenase (OGDH)." (PMID 37512582, 2023). "Among the 17 analyzed NRGs in various types of cancer, mutations of PIK3CA were prevalent in a variety of cancer types." (PMID 37408763, 2023). "We observe that PIK3CA has a relatively high hazard ratio (OS HR 1.33, N = 129, P = 0.03), suggesting its association with a worse prognosis in dogs with cancer." (PMID 36658200, 2023). "It has also been proposed as a drug target in PTEN‐deficient cancers and in PI3Kα inhibitor‐resistant PIK3CA mutant cancers." (PMID 36423211, 2023). "Taselisib, a β-sparing inhibitor (targeting all class I isoforms but PI3Kβ) has been recently tested in a phase I clinical trial in PIK3CA-mutated cancers." (PMID 36765741, 2023). "According to TCGA, typical gene mutations for HPV-associated cancers include PIK3CA, FGFR, DDX3X, and CYLD." (PMID 37299554, 2023). "Given this proven relationship between PIK3CA mutations and cancer, a higher risk for malignancy would be expected in individuals with PROS." (PMID 38136956, 2023).